SIRT1 (sirtuin 1)
Diseases named in the same sentence as SIRT1 in open-access papers (continued):
Sharing a sentence is not in itself a finding about the gene and the disease.
cardiac hypertrophy (continued). "AMPK activation inhibits myocardial hypertrophy by regulating energy metabolism through sirtuin 1 (SIRT1)." (PMID 33762947, 2021). "At the cardiac level, the activation of the SIRT1-PGC-1α axis inhibits cardiac hypertrophy, characteristic of dystrophic models, and improves cardiac function." (PMID 34205021, 2021). "In the heart, Sirt1 can modulate fatty acid oxidation, cardiac hypertrophy, apoptosis, oxidative stress, and autophagy." (PMID 33073318, 2021). "SIRT1 in heart is known to provide cardio-protection in conditions like hypertrophy and myocardial infarction." (PMID 32335547, 2020). "The haploinsufficiency of either PPARα or SIRT1 reduces pressure overload-induced cardiac hypertrophy and failure, whereas the simultaneous induction of PPARα and SIRT1 aggravates cardiac dysfunction." (PMID 32708786, 2020). "Namely, in vivo activation of SIRT1 protects against cardiac hypertrophy, metabolic dysregulation, and cardiac inflammation in a mouse model of cardiac hypertrophy, and exhibits protective effects in other models of cardiac dysfunction." (PMID 32486488, 2020). "Some data report a relationship between increased Sirt1 levels and cardiac hypertrophy, while other data suggest that low-moderate Sirt1 overexpression has beneficial effects in contrasting fibrosis and hypertrophy." (PMID 33238655, 2020). "Recently, pharmacologic studies have suggested that FGF21 improves cardiac function and alleviates Ang II-induced cardiac hypertrophy in a SIRT1-dependent manner." (PMID 32210821, 2020). "In the present study, accompanied by an alleviated hypertrophic phenotype, hispidulin was able to upregulate Sirt1 expression in the presence of pressure overload-induced cardiac hypertrophy as well as in isolated adult mouse cardiomyocytes." (PMID 33324687, 2020). "The upregulation of Sirt1 induced by resveratrol protects the heart against isoproterenol-induced cardiac hypertrophy." (PMID 33324687, 2020). "In a study performed by Alcendor's group, SIRT1 protected cardiomyocytes from death under stress conditions, promoted cardiomyocyte growth, and led to cardiac hypertrophy." (PMID 31866862, 2019). "It was shown that the activation of Sirt1 (Sirtuin 1) pathway prevents the development of cardiac hypertrophy and protects cardiac cells from inflammation and metabolic dysregulation." (PMID 30671457, 2018). "Surprisingly, however, it was observed that Sirt1 KO mice were protected from cardiac hypertrophy in response to pressure overload." (PMID 29497772, 2018). "Altogether, inactivation of Sirt1 in cardiomyocytes led to symptoms characteristic for diabetic cardiomyopathy (DCM) including cardiac hypertrophy, abnormal glucose metabolism and insulin resistance." (PMID 29497772, 2018). "For instance, Sirt1 activation has been shown to ameliorate cardiac hypertrophy and fibrosis and restore cardiac diastolic function in dystrophic mice." (PMID 29497772, 2018). "Studies have shown that Sirt1 can protect the heart from external stress, inflammation and cardiac hypertrophy; Sirt3 and Sirt7 in the heart of the stress response process also plays an extremely important role." (PMID 28582407, 2017). "Cardiac function in SIRT1KO mice was markedly reduced as compared with that in WT mice, accompanied with cardiac hypertrophy and fibrosis, indicating the crucial role of SIRT1 in cardiac function." (PMID 28883902, 2017). "On the other hand, 12.5 fold increase in SIRT1 level promoted cardiac hypertrophy, induced apoptosis and promoted cardiomyopathy." (PMID 28258519, 2017). "For example, moderate expression of SIRT1 attenuates the age‐dependent incidence of cardiac hypertrophy and dysfunction by inducing cardiac resistance to oxidative stress in mice." (PMID 26637971, 2016). "In conclusion, our current findings show that ETS exposure can reduce the Sirt-1 level in hearts, enhance the activation of the cardiac hypertrophy-related IGF2R signaling pathway and enhance cardiac autophagy." (PMID 27167200, 2016).
cardiac hypertrophy (continued). "Several studies support a role for miR-22 in cardiac hypertrophy via targeting Pten, Sirtuin 1 (Sirt1), and histone deacetylase 4 (Hdac4) as evidenced by results from transgenic mouse models and multiple induced-hypertrophic cellular platforms." (PMID 27213331, 2016). "Enhancing the SIRT1 function mitigates ischemia/reperfusion-induced cardiac hypertrophy and myocardial dysfunction." (PMID 26885898, 2016). "Sirt1, Sirt3 and Sirt6 have also demonstrated to attenuate cardiac hypertrophy, and protect cardiomyocytes from aging and oxidative stress." (PMID 27690014, 2016). "Here, we determined the mechanism by which SIRT1 regulates Angiotensin II- (AngII-) induced cardiac hypertrophy and injury in vivo and in vitro." (PMID 25614777, 2014). "Here, we provided novel insight into how SIRT1 was involved in estrogen-mediated heart protection effect in Angiotensin II-induced heart hypertrophy and cardiomyocyte apoptosis." (PMID 25614777, 2014). "The studies of SIRT1's function in heart hypertrophy are controversial; some data suggested that SIRT1 promoted cardiomyocyte hypertrophy; others indicated that SIRT1 attenuated cardiomyocyte hypertrophy." (PMID 25614777, 2014). "Protein synthesis, cardiomyocyte surface area analysis, qRT-PCR, TUNEL staining, and Western blot were performed on AngII-induced mouse heart hypertrophy samples and cultured neonatal rat ventricular myocytes (NRVMs) to investigate the function of SIRT1." (PMID 25614777, 2014). "These in vivo data suggest that SIRT1 was involved in heart hypertrophy development and was correlated with E2's protection effect in hearts." (PMID 25614777, 2014). "SIRT1 and SIRT3 appear to share similarROS-accumulating end-point targets that cause cardiac hypertrophy." (PMID 20375467, 2010). "Circulating IGF-1 and SirT1 have both been implicatedin the protection against cardiac hypertrophy,although the role of IGF-1 and/or its isoforms in this process remainscontroversial." (PMID 20228935, 2009). "NAD+-dependent SIRT1 is essential for the maintenance of normal heart function and a moderate increase in SIRT1 levels has been shown to retard cardiac aging by attenuating cardiac hypertrophy, apoptosis/fibrosis, and cardiac dysfunction." (PMID 40695797, 2025). "Circ-SIRT1 inhibits cardiac hypertrophy by promoting autophagy by activating SIRT1." (PMID 38172650, 2024). "Circ_SIRT1 could mediate miR-3681-3p to affect SIRT1 expression and promote autophagy to alleviate cardiac hypertrophy." (PMID 38698487, 2024). "By promoting mitochondrial biogenesis, structural integrity, antioxidant protein expression, and the destruction of dysfunctional ROS-producing mitochondria via mitophagy, SIRT1 ameliorates oxidative stress-induced myocardial hypertrophy, MEC injury, and apoptosis." (PMID 39598406, 2024). "SIRT1 can protect against pathological cardiac hypertrophy in addition to activating UPRmt." (PMID 38278820, 2024). "Thus, SIRT1 and estradiol can be indicated as the targets and agents of therapies treating cardiac hypertrophy and protecting against the development of heart failure associated with its remodeling." (PMID 37762053, 2023). "Sirt1 deletion protects against pressure overload (PO)-induced cardiac hypertrophy; however, low-level overexpression of SIRT1 in the heart attenuates age-associated cardiac hypertrophy, fibrosis, and cardiac dysfunction, while high-level overexpression of SIRT1 increases these pathological effects." (PMID 37728319, 2023). "Histidine attenuates pressure overload and phenylephrine (PE)-induced myocardial hypertrophy through upregulation of SIRT1, which prevents mitochondrial dysfunction and oxidative damage in response to hypertrophic stimuli and maintains mitochondrial respiratory function and ATP synthesis." (PMID 36843938, 2023).
cardiac hypertrophy (continued). "Also, PPARα-Sirt1 complex attributes to cardiac hypertrophy and failure by suppressing the ERR transcriptional pathway." (PMID 36385157, 2022). "Moreover, one study provided the first evidence that NBR2 is relevant with myocardial hypertrophy by finding that NBR2 inhibits endoplasmic reticulum (ER) stress and myocardial hypertrophy by modulating the LKB1/AMPK/Sirt1 pathway." (PMID 36233294, 2022). "Based on these findings, we hypothesized that FGF20 prevented cardiac hypertrophy by activating SIRT1-mediated antioxidant defenses." (PMID 35351862, 2022). "In addition, overexpressing NBR2 facilitated the LKB1/AMPK/Sirt1 profile, thereby alleviating myocardial hypertrophy and ER stress in HCM and AC16 cells." (PMID 35703318, 2022). "However, potential mechanisms targeting the biological role of lncRNAs and LKB1/AMPK/SIRT1 in myocardial hypertrophy remain obscure." (PMID 35703318, 2022). "Of note, SIRT1 might have bidirectional effects on cardiac hypertrophy, which might be dependent on the degree of SIRT1 expression." (PMID 36581622, 2022). "In summary, our findings reveal a previously unknown protective effect of FGF20 on pathological cardiac hypertrophy by reducing oxidative stress through activation of the SIRT1 signaling pathway." (PMID 35351862, 2022). "After SIRT1 knockout, the indexes of myocardial hypertrophy β-MHC and ANP increase." (PMID 36204518, 2022). "The relationship between lncRNAs and the LKB1/AMPK/Sirt1 has been clearly understood, but the impact of the LKB1/AMPK/Sirt1 pathway on myocardial hypertrophy remains largely unknown." (PMID 35703318, 2022). "However, different levels of SIRT1 overexpression seem to play a dual role in promoting or inhibiting the development of cardiac hypertrophy." (PMID 35958418, 2022). "GB inhibits Ang II-induced cardiac hypertrophy by enhancing autophagy via the SIRT1-FoxO1 signaling pathway and might be a potential agent in treating pathological cardiac hypertrophy." (PMID 34257705, 2021). "In addition, SIRT1 is involved in cardiac angiogenesis in response to cardiac hypertrophy by regulating AKT activity, which subsequently affects mTOR activity." (PMID 33806509, 2021). "Based on these results and given that both Sirt1 and P300 participate in the regulation of cardiac hypertrophy, we hypothesized that these two proteins may act coordinately." (PMID 33594087, 2021). "In vivo, similar findings were observed in a diabetic cardiomyopathy murine model (gender not specified), as resveratrol (25 mg/kg/d for five days) significantly increased Sirt1, reduced cardiac hypertrophy, and improved ejection fraction, but this was abrogated by Sirt1-specific cardiac deletion." (PMID 33513742, 2021). "Meanwhile, we discovered that Sirt1 blockage diminished the protective effect of hispidulin on cardiac hypertrophy, which indicated that Sirt1 might interact with hispidulin correspondingly in regulating cardiac hypertrophy." (PMID 33324687, 2020). "However, silencing of miR-195 expression inhibited oxidative stress, alleviated myocardial hypertrophy and improved cardiac function in diabetic mice, while at the same time the cardiac levels of B-cell lymphoma 2 (Bcl-2) and SIRT1 were upregulated." (PMID 33537003, 2020). "Up-regulation of SIRT1 has a cardio-protective effect while inhibiting its activity in cardiomyocytes results in an increase in the rate of apoptosis and myocardial gene-related hypertrophy." (PMID 32082101, 2020).
cardiac hypertrophy (continued). "Previous studies showed that the Nampt/NAD/Sirt1 axis has a protective effect in several heart diseases through elimination of oxidative stress, including ischemic heart disease, cardiomyopathy, pressure-overload heart failure, and cardiac hypertrophy." (PMID 32629939, 2020). "Moreover, pharmacological inhibition of Sirt1 abolished most of the protective effects of hispidulin, represented as aggravated cardiac hypertrophy, impaired cardiac function, and reduced expression of ETC subunits." (PMID 33324687, 2020). "The SIRT1/PGC‐1α pathway is an important signalling pathway in myocardial hypertrophy." (PMID 32757458, 2020). "However, Sirt1 expressed at high level (12.5-fold) shortens lifespan and induces cardiac hypertrophy, fibrosis, apoptosis and results in LV dysfunction at 6 months of age." (PMID 32085438, 2020). "Similarly, some studies suggest that SIRT1 expression levels are elevated in cardiac hypertrophy and heart failure." (PMID 31866862, 2019). "Low to moderate level of SIRT1 expression (2.5 to 7.5 times higher than endogenous level) has a protective effect on age-dependent myocardial hypertrophy, apoptosis, and cardiac insufficiency, whereas high levels (12.5-times) can induce dilation, hypertrophy, and heart failure." (PMID 31866862, 2019). "In addition, in some pathophysiological conditions, including cardiac hypertrophy and tumor progression, Sirt1 clearly activates protective signaling pathways controlled by AKT and PDK1." (PMID 30304806, 2018). "In cardiac hypertrophy, Sirt1 may act in the cytosol, where it deacetylases Akt and PDK1, PDK1 phosphorylates Akt, which becomes active and promotes hypertrophy." (PMID 30304806, 2018). "Notably, in untrained CHF patients, Sirt1 in significantly down-regulated, a phenomenon that has been seen also in cardiac hypertrophy and in the presence of pressure overload." (PMID 30304806, 2018). "In addition, low to moderate overexpression of Sirt1 (2.5–7.5 times) mitigates cardiac hypertrophy induced by aging, provides protection against oxidative stress-induced cardiotoxicity, and improves endothelial function." (PMID 29234485, 2017). "Our results suggest that though ETS exposure might cause cardiac autophagy amongst youngsters, the loss of the longevity Sirt-1 protein and the increase in IGF2R cardiac hypertrophy signaling could still promote heart diseases that are age-specific." (PMID 27167200, 2016). "However, contradictory phenotypes attributable to gene dosages of the transgene were observed in the development of cardiac hypertrophy in mice with cardiac overexpression of Sirt1." (PMID 26522369, 2015). "In the present study, we found that SIRT1 was slightly regulated in heart hypertrophy mouse model and AngII-treated NRVMs, indicating that SIRT1 might act as an inner protective regulator in hearts." (PMID 25614777, 2014). "The dysregulation of SIRT1 may be a common feature of the development of heart hypertrophy and therefore represents a potential therapeutic target." (PMID 25614777, 2014). "This domain isconsidered of clinical interest for the treatment of cardiovascular diseases, and themIGF-1/SirT1 pathway presented in this study may represent a promisingtherapeutic target to fight cardiac hypertrophy and oxidative stress." (PMID 20228935, 2009). "Together, these results are consistent with the cardioprotective effects of roflumilast, suggesting that reducing the abundance of PDE4D may provide an effective strategy to protect against cardiac hypertrophy and mitochondrial dysfunction by modulating SIRT1-mediated mitophagy." (PMID 40015131, 2025). "Inhibition of SIRT1 could reverse the protective effect of histidine on myocardial hypertrophy." (PMID 36843938, 2023). "Therefore, we examined whether FGF20 protects against cardiac hypertrophy by activating SIRT1 via detecting the protein and transcriptional levels of SIRT1 in vitro and in vivo." (PMID 35351862, 2022).
cardiac hypertrophy (continued). "Meanwhile, SIRT1 and 3 interact with nuclear and mitochondrial proteins, to mediate energy metabolism and ATP synthesis, which may also be a critical step leading to cardiac hypertrophy." (PMID 35958418, 2022). "Finally, the effect of GB on autophagy and cardiac hypertrophy could be reversed by SIRT1 inhibitor EX-527." (PMID 34257705, 2021). "A number of studies have reported that SIRT1, one of the members of class III histone deacetylases enzymes, inhibits apoptosis in cardiomyocytes and its reduction is associated with various cardiovascular pathologies such as cardiac hypertrophy and the severity of heart failure." (PMID 34354599, 2021). "Previous studies showed that SIRT1 activation could reduce Ang II-induced cardiac hypertrophy." (PMID 34257705, 2021). "Thus, our findings suggest that Sirt1 might be a downstream effector of hispidulin in regulating cardiac hypertrophy." (PMID 33324687, 2020). "In fact, high levels of Sirt1 (more than 12 times above the normal level) have detrimental effects on the cardiac function, while a low to moderate overexpression of Sirt1 in transgenic mice inhibits age-dependent development of cardiac hypertrophy and fibrosis." (PMID 29497772, 2018). "Moreover, the effect of Sirt2 on Akt activation, similar to that of Sirt1, suggests that its activation could prevent cardiac hypertrophy." (PMID 30304806, 2018). "In a clinical context, this study identifies hopeaphenol as a promising therapeutic candidate for cardiac hypertrophy, emphasizing the significance of the AMPK/SIRT1 signaling pathway in ameliorating myocardial metabolic disorders." (PMID 41010549, 2025). "AMPK/SIRT1 pathway activation by S1pr1 regulation decreased ISO-induced ERS and cardiac hypertrophy." (PMID 40191425, 2025). "SIRT1 and SIRT3 protect cardiomyocytes by enhancing the deacetylation of PGC-1α, reducing oxidative stress, and inhibiting the occurrence of cardiac hypertrophy." (PMID 40710369, 2025). "Overall, Rg3 combats Ang II-induced myocardial hypertrophy by deactivating the NLRP3 inflammasome and oxidative stress via the SIRT1/NF-κB pathway." (PMID 39108942, 2024). "Circ-SIRT1 delivery sponges miR-3681-3p/5195-3p and miR-132/212 to stabilize SIRT1 protein from degradation and enhance SIRT1 expression, inhibiting cardiac hypertrophy and ameliorating VSMC inflammation via SIRT1/NF-κB signaling." (PMID 39598406, 2024). "In conclusion, this study shows that CTRP3 activated UPRmt through the SIRT1/ATF5 axis and alleviated mitochondrial dysfunction and oxidative stress injury under pathological cardiac hypertrophy." (PMID 38278820, 2024). "The upregulation of SIRT1, PGC-1α, and AMPK, along with inhibition of the Akt/mTOR pathway, promotes autophagy, diminishes myocardial hypertrophy, and improves heart failure." (PMID 37754811, 2023). "Drp1 and YAP, which can regulate mitochondria through SIRT1/MFN2, can reduce gastric cancer survival and migration, and attenuate mitochondrial dysfunction in cardiac hypertrophy." (PMID 37895915, 2023). "The expression of SIRT1, SIRT3, and PGC-1α (Peroxisome proliferator-activated receptor gamma coactivator-1 alpha) were decreased in cardiac hypertrophy." (PMID 35958418, 2022). "SIRT1 and SIRT3 enhance the deacetylation of PGC-1α, reduce oxidative stress and prevents cardiac hypertrophy." (PMID 35958418, 2022). "Liraglutide significantly attenuated cardiac hypertrophy, pathological changes, inflammation, pyroptosis, and NLRP3 inflammasome activation, accompanied by increased Sirt1 and AMPK activation." (PMID 35096293, 2021). "Recently, studies have reported that SIRT1 contributes to cardiac metabolism by activating PGC‐1α and pyruvate dehydrogenase kinase 4 (PDK4) expressions during cardiac hypertrophy." (PMID 32757458, 2020). "Protein kinase C (PKC)-ζ leads to cardiac hypertrophy via increased activity of nuclear factor-kappaB (NF-κB), ERK1/2 and ERK5, which sirtuin-1 prevents via PKC-ζ inhibition, as shown in preclinical models." (PMID 31434333, 2019).